ABHD2 (abhydrolase domain containing 2, acylglycerol lipase)
Diseases named in the same sentence as ABHD2 in open-access papers:
ABHD2 is named in the same sentence as 34 diseases in open-access papers, as found by Europe PMC text mining. Sharing a sentence is not in itself a finding about the gene and the disease. The quoted sentences say what the papers report.
prostate carcinoma (6 papers, 2010 to 2024). A carcinoma that arises from epithelial cells of the prostate gland. "Since it is an androgen-regulated gene that is associated with the development of prostate cancer and its ability to resist chemotherapy, ABHD2 is a promising new target for prostate cancer screening and treatment." (PMID 36468011, 2022). "ABHD2 is a novel androgen-regulated gene that can enhance prostate cancer growth and chemotherapy resistance." (PMID 38773226, 2024). "ABHD2, an androgen target gene, was reported to promote prostate cancer cell proliferation and migration." (PMID 35054064, 2022). "Further investigations with different systems biology methods have prioritized NR3C1, ABHD2, and GSK3B as potential genes involved in prostate cancer metastasis owing to their high mutation load and expression status." (PMID 36468011, 2022). "For instance, stable expression of ABHD2 in LNCaP cells promoted cell proliferation and enhanced cell migration, whilst inhibition of ABHD2 transcription suppressed prostate cancer growth and induced cell apoptosis." (PMID 32695121, 2020). "According to these results, ABHD2 was proposed as a novel target for the diagnosis and treatment of prostate cancer." (PMID 32816024, 2020). "Interestingly, in 5/9 genes (55.5%), i.e., ABHD2, DICER1, GSK3B, NR3C1, and NFIB mutations were localized to functional domains of their corresponding proteins, which suggest them to be highly critical genes for prostate cancers." (PMID 36468011, 2022). "In comparison, there were no obvious associations between the expression levels of ABHD2, FGF2, DCAF7, GSK3B, NACC2, DICER1, and FGFR1OP genes and survival rate in prostate cancer patients." (PMID 36468011, 2022). "Additionally, ABHD2 is targeted by antibody molecules, and GSK3B is targeted by lithium carbonate inhibitor which has currently completed phase 1 trial in prostate cancer." (PMID 36468011, 2022). "The other genes showing molecular alterations in prostate cancer samples from highest to lowest are as follows; FGF2 (94/4990; 1.9%), NFIB (86/4990; 1.7%), CEP43 (62/4990; 1.2%), GSK3B (99/8961; 1.1%), DICER1 (101/8961; 1.1%), NR3C1 (53/4990; 1.1%) and ABHD2 (28/4,990; 0.6%)." (PMID 36468011, 2022).
serous ovarian cancer (5 papers, 2016 to 2021). "In clinical serous ovarian cancer specimens, low expression of ABHD2 was associated with platinum resistance and poor prognosis (p<0.05, respectively)." (PMID 27323405, 2016). "In humans, downregulation of ABHD2 expression resulted in anoikis resistance in high-grade serous ovarian cancer." (PMID 34568325, 2021). "Studies have suggested that the expression inhibition of ABHD2 may promote a malignant phenotype and contribute to an adverse prognosis in patients with serous ovarian cancer." (PMID 29794032, 2018). "Suppression of ABHD2 may promote a malignant phenotype and poor prognosis for women with serous ovarian cancer." (PMID 27323405, 2016). "In addition, the expression of ABHD2 is lower in clinical serous ovarian cancer specimens." (PMID 29794032, 2018).
emphysema (4 papers, 2015 to 2023). "These Abhd2-deficient mice had increased lung macrophage infiltration and inflammatory markers and spontaneously developed emphysema with aging." (PMID 37523383, 2023). "Abhd2-deficient mice generated via gene trap insertional mutagenesis developed spontaneous, gradual emphysema." (PMID 25880496, 2015). "ABHD2 deficient mice develop spontaneous gradual progression of emphysema." (PMID 27323405, 2016). "Using this method, 14 new selection loci for resistance and susceptibility to gastrointestinal nematodes have been found in sheep, the gene ABHD2 related to emphysema and the gene BMP2 related to the bone morphology and body type of animals." (PMID 33708236, 2021). "The human α/β hydrolase domain-containing protein 2 gene (ABHD2) plays a critical role in pulmonary emphysema, a major subset of the clinical entity known as chronic obstructive pulmonary disease (COPD)." (PMID 25880496, 2015). "Our results showed that derangement of alveolar phospholipid metabolism could induce emphysema and that Abhd2 played a critical role in maintaining lung structural integrity." (PMID 25880496, 2015).
breast carcinoma (3 papers, 2021 to 2023). "Further studies will be required to reveal the detailed roles and respective mechanisms of ABHD2 in breast cancer." (PMID 36125462, 2023). "Through online database analysis and dual‐luciferase experiments, we supposed that ABHD2 may be a direct target of miR‐33a‐5p in breast cancer cells." (PMID 36125462, 2023). "It is reported that the expressions of ABHD2 in breast cancer and melanoma are obviously higher than those in normal tissues, but whether it has molecular functions in these two cancers is still unknown." (PMID 35963893, 2022). "Through this study, we could gain an in‐depth understanding of the role of vaspin/miR‐33a‐5p/ABHD2 in obese and overweight TNBC, thus better understanding the mechanism of breast cancer deterioration in obese and overweight people." (PMID 36125462, 2023). "High expression of ABHD2 is detrimental to DFS and OS of breast cancer patients." (PMID 36125462, 2023). "Currently, there was no report on the role of ABHD2 in breast cancer." (PMID 36125462, 2023). "In conclusion, we found that compared with normal weight breast cancer patients, serum vaspin level in overweight patients significantly increased, and vaspin could promote the progression of TNBC by regulating the miR‐33a‐5p/ABHD2 pathway." (PMID 36125462, 2023).
cervical cancer (3 papers, 2020 to 2025). A primary or metastatic malignant neoplasm involving the cervix. "In follow-up experiments, we will further explore the specific roles of ABHD2/NUDT21 in the development of HPV16-positive cervical cancer and its related mechanisms." (PMID 32816024, 2020). "This work is expected to provide new insights into the mechanism by which HPV16 E6/E7 regulate ABHD2/NUDT21 through miR-4454 to better understand the malignant transformation of cervical cancer." (PMID 32816024, 2020). "In conclusion, miR-4454 was overexpressed in HPV16 positive cervical cancer cells, and HPV16 E6/E7 may affect cancer cell invasion and migration via miR-4454/ABHD2/NUDT21 axis in cervical cancer cells." (PMID 32816024, 2020).
chronic obstructive pulmonary disease (2 papers, 2015 to 2018). A chronic and progressive lung disorder characterized by the loss of elasticity of the bronchial tree and the air sacs, destruction of the air sacs wall, thickening of the bronchial wall, and mucous accumulation in the bronchial tree. "ABHD2 was found to be a critical gene in chronic obstructive pulmonary disease (COPD) by evaluating the genetic variation in the ABHD2 gene among Han Chinese COPD patients and normal controls." (PMID 29794032, 2018).
hepatocellular carcinoma (2 papers, 2022 to 2024). A malignant tumor that arises from hepatocytes. "TDP43 can bind to the UG-rich sequence in 3′ UTR of ABHD2 mRNA and enhance its stability, further suppressing hepatocellular carcinoma cell apoptosis." (PMID 39510185, 2024).
lung carcinoma (2 papers, 2016 to 2021). "This functionality justifies the increase in expression of human ABHD2 gene in breast and lung cancers, supporting the necessary energy by the breakdown of lipids for the accelerated proliferation of cancer cells." (PMID 27247428, 2016). "Though, human ABHD2 gene was found to be highly expressed in breast and lung cancers, its biochemical functionality is yet uncharacterized." (PMID 27247428, 2016).
ovarian carcinoma (2 papers, 2016 to 2019). A malignant neoplasm originating from the surface ovarian epithelium. "However, the response gene of miR-485, Abhd2, was reported to be able to suppress the phosphorylation of Erk1/2 in ovarian cancer and our study showed that Abhd2 had the same effect during the differentiation of F9 ECs." (PMID 31035455, 2019). "We therefore focused on the role of ABHD2 in ovarian cancer." (PMID 27323405, 2016). "Like ABHD2, ELAC2 and CYB5R3 mRNA levels were significantly lower in ovarian cancer than in SBT (p=0.008 and 0.003, respectively)." (PMID 27323405, 2016). "In summary, altered ABHD2, ELAC2 and CYB5R3 mRNA expression was identified through our functional genomics screen and was significantly reduced in ovarian cancer, especially in HGSOC, relative to that in SBT or normal ovarian epithelium." (PMID 27323405, 2016). "In accordance with this result, in two expression microarray datasets of ovarian cancer consisting mostly of HGSOC (GSE9891, GSE3149), the prognosis of the low ABHD2 expression group was significantly worse as compared to that of the high ABHD2 expression group (p=0.013, p=0.04, respectively)." (PMID 27323405, 2016).
Stroke (2 papers, 2022 to 2025). Sudden impairment of blood flow to a part of the brain due to occlusion or rupture of an artery to the brain. "Another gene in common was ABHD2 (Abhydrolase Domain Containing 2, Acylglycerol Lipase), which is known to interact with proteins associated with neurodegeneration, type 2 diabetes, and stroke." (PMID 36079709, 2022).
age-related macular degeneration (1 paper, 2023). Age-related loss of vision in the central portion of the retina (macula), secondary to retinal degeneration. "Recently, the Abhd2 locus was linked to age-related macular degeneration (AMD) through a human GWAS of mitochondrial variants." (PMID 37523383, 2023).
atherosclerosis (1 paper, 2023). A disease characterized by the build-up of fatty material and calcium deposition in the arterial wall resulting in partial or complete occlusion of the arterial lumen. "Previous studies have found that ABHD2 played a key role in the infiltration of macrophages into atherosclerosis." (PMID 36125462, 2023).
colon cancer (1 paper, 2024). "To validate our data analysis results, we extracted total RNA from patient colon cancer tissue and corresponding normal colon epithelial tissue and measured the mRNA expression levels of TIMP1, VEGFA, MYC, MSLN, EPHA2, ABHD2, and CD24." (PMID 38773226, 2024).
COVID-19 (1 paper, 2024). A disease caused by infection with severe acute respiratory syndrome coronavirus 2. "Although no the direct evidence links ABHD2 to COVID-19 and the neurological diseases, its role in regulating the male fertility is intriguing, as COVID-19 has been associated with the male infertility." (PMID 39469068, 2024).
cyst (1 paper, 2021). A sac-like closed membranous structure that may be empty or contain fluid or amorphous material. "NGF signaling is also elevated in women with PCOS, while increased NGF signaling causes mice to show signs of PCOM, with a higher number of atretic antral follicles, without displaying cyst formation—the phenotype we also observed in Abhd2–/– females." (PMID 34568325, 2021).
glioblastoma (1 paper, 2020). The most malignant astrocytic tumor (WHO grade IV). "PREX1 and ABHD2 have also shown to promote tumor invasion and progression in glioblastoma, while the tumor suppressor BIN1 was found to be regulated by HNRNPA2B1, a putative proto-oncogene in GBM." (PMID 32070274, 2020).
lung adenocarcinoma (1 paper, 2023). A carcinoma that arises from the lung and is characterized by the presence of malignant glandular epithelial cells. "ABHD2 was found to be significantly downregulated in lung adenocarcinoma tissue samples (TCGA database) from others and the AUC value of ABHD2 in lung adenocarcinoma was 0.733." (PMID 37252659, 2023). "Therefore, hsa-miR-619-5p and hsa-miR-4454 may regulate the occurrence and development of lung adenocarcinoma by regulating their downstream gene ABHD2." (PMID 37252659, 2023).
lymph node metastasis (1 paper, 2016). "We investigated the relationship between ABHD2 protein expression and clinicopathological factors in HGSOC, including patient age, FIGO stage, ascites cytology, lympho-vascular invasion (LVSI), lymph node metastasis, platinum resistance and prognosis." (PMID 27323405, 2016).
macular degeneration (1 paper, 2023). Loss of vision in the central portion of the retina (macula), secondary to retinal degeneration. "We observed a reduction in CL in livers of Abhd2KO mice; thus, we are tempted to speculate that Abhd2 deficiency may contribute to macular degeneration through its effects on CL." (PMID 37523383, 2023).
ovarian clear cell cancer (1 paper, 2016). An invasive malignant neoplasm that arises from the ovary and is characterized by a predominance of clear and hobnail malignant epithelial cells. "We overexpressed or suppressed ABHD2 expression in RMG1, an ovarian clear cell carcinoma cell line." (PMID 27323405, 2016).
polycystic ovary (1 paper, 2021). "Interestingly, the ovaries of Abhd2 knockout (KO) females resemble polycystic ovary morphology (PCOM) with a high number of atretic antral follicles that could be rescued with injection of gonadotropins." (PMID 34568325, 2021).
skin melanoma (1 paper, 2023). "For example, ABHD2 is a direct target of miR‐140‐3p in skin melanoma cells." (PMID 36125462, 2023).
cancer (13 papers, 2015 to 2025). A tumor composed of atypical neoplastic, often pleomorphic cells that invade other tissues. "α/β-hydrolase domain-containing 2 (Abhd2), which is a member of the alpha/beta hydrolase family, is also involved in cancer but few reports have implicated either of these molecules in cell differentiation." (PMID 31035455, 2019). "In addition, the level of ABHD2 gene expression is altered in cancers, and its normal function has been implicated in tumour cell proliferation and survival." (PMID 40008534, 2025). "The intimal cell hyperplasia caused by suppression of ABHD2 might be related to apoptosis resistance observed in cancer cells." (PMID 27323405, 2016). "Furthermore, they found that the phosphorylation of Erk1/2 can be up-regulated by inhibiting Abhd2 in cancer cells." (PMID 31035455, 2019). "Indeed, immunohistochemical analysis of tumor specimens has shown a positive correlation of ABHD2 levels with high Gleason score, pathological nodal stage, low cancer-specific survival rates, and a resistance to docetaxel-based chemotherapy." (PMID 30367117, 2019). "Recent studies have shown that ABHD2 could promote cancer progression." (PMID 36125462, 2023). "Notably, few studies have addressed the role of ABHD2 in malignant tumors." (PMID 35963893, 2022). "The results showed that ABHD2, DCAF7, and GSK3B were upregulated in cancer tissues compared with normal prostate tissues with high or medium intensity." (PMID 36468011, 2022). "Vaspin, as a cancer‐promoting cytokine, may inhibit miR‐33a‐5p thus increasing the level of ABHD2 to promote the development of the triple‐negative breast cancer." (PMID 36125462, 2023). "In cancer, miR-140-3p usually acts as cancer suppressor, such as suppressing cell growth in colorectal cancer by PD-L1, suppressing growth and invasion of cell lung cancer by down-regulating ATP8A1, and inhibiting progression of cutaneous melanoma by targeting ABHD2." (PMID 35120526, 2022).
tumor (10 papers, 2017 to 2025). "The results showed that overexpression of ABHD2 effectively alleviated the inhibition of tumor growth caused by TDP-43 deletion." (PMID 35963893, 2022). "We found that TDP-43 deficiency could reduce the expression of ABHD2 in tumor tissues." (PMID 35963893, 2022). "ABHD2 regulates extracellular matrix and cell–cell interactions, influencing tumour invasion and metastasis." (PMID 40008534, 2025). "In our differential gene expression analysis and GSEA, most enriched genes are involved in tumor aggressiveness and drug resistance including ABHD2, ABCC4, CLN5 intracellular trafficking protein, and insulin like growth factor 2 receptor." (PMID 35054064, 2022). "The cells (MHCC97H-Control + vector, MHCC97H-KD-TDP-43 + vector and MHCC97H-KD-TDP-43 + ABHD2) were collected for subcutaneous tumor implantation in nude mice." (PMID 35963893, 2022). "In conclusion, our data suggested that ABHD2 had significance in tumor development and was expected to be a potential target for the precise treatment of HCC." (PMID 35963893, 2022). "Meanwhile, the expression levels of ABHD2 in mice tumor tissues were determined by IHC staining assay." (PMID 35963893, 2022). "Recent studies described that the ABHD2 gene may contribute to the process of multiple tumour development, invasion and metastasis." (PMID 40008534, 2025). "Given the role of ABHD2 in fatty acid metabolism, we speculate that this gene might play a valuable part in tumour growth and progression through metabolic reprogramming of tumour cells." (PMID 40008534, 2025). "These evidences revealed that with the help of ABHD2, TDP-43 regulated lipid metabolism, which had an impressive effect on tumor cell apoptosis." (PMID 35963893, 2022). "Results showed that the expression of five parent gene (PRIM2, ABCC4, UTRN, ABHD2, and MTHFD2L) was also significant increase in tumor compared to those in normal tissues." (PMID 34852706, 2021).
ABHD2 also shares sentences with these, for which no sentence is quoted: colorectal cancer (2 papers); melanoma (2); Granuloma (1); Hepatitis (1); immune disorders (1); male infertility (1); neurological diseases (1); Ovarian cyst (1); prostate adenocarcinoma (1); type 2 diabetes (1).